WEE2 (WEE2 oocyte meiosis inhibiting kinase)
Description:
Oocyte-specific protein tyrosine kinase that phosphorylates and inhibits CDK1/CDC2 and acts as a key regulator of meiosis during both prophase I and metaphase II. Required to maintain meiotic arrest in oocytes during the germinal vesicle (GV) stage, a long period of quiescence at dictyate prophase I, by phosphorylating CDK1 at 'Tyr-15', leading to inhibit CDK1 activity and prevent meiotic reentry. Also required for metaphase II exit during egg activation by phosphorylating CDK1 at 'Tyr-15', to ensure exit from meiosis in oocytes and promote pronuclear formation (By similarity).
Synonyms: WEE1B; FLJ16107; OOMD5; OZEMA5
Tractability: Small molecule: a structure with a bound ligand is known; a high-quality ligand is known; it belongs to a druggable protein family. Antibody: its Gene Ontology location is reachable by antibodies, with high confidence. PROTAC: a small molecule that binds it is known.
Target class: Protein Kinase; Kinase; Other protein kinase group; Other protein kinase WEE family; Enzyme; Other protein kinase WEE1
Gene: Protein-coding gene on chromosome 7 (141,702,227 to 141,731,271, forward strand). Ensembl gene ENSG00000214102.
Subcellular location: Nucleus
Subcellular location (Human Protein Atlas): Nucleoplasm
Gene Ontology:
Molecular function: protein tyrosine kinase activity; ATP binding; magnesium ion binding; non-membrane spanning protein tyrosine kinase activity; protein kinase activity
Biological process: female meiotic nuclear division; female pronucleus assembly; negative regulation of oocyte maturation; regulation of meiosis I; mitotic cell cycle; positive regulation of phosphorylation; regulation of fertilization
Cellular component: nucleoplasm; nucleus; cytoplasm
Genetic constraint (gnomAD): Loss-of-function variants: 48 observed, 59.21 expected, observed/expected ratio (o/e) 0.81, 90% interval 0.64 to 1.03. The upper end of that interval is the gene's LOEUF score, 1.03, which puts it in group 4 of 6, group 1 being the genes least tolerant of losing a copy. Missense variants: 621 observed, 711.98 expected, observed/expected ratio (o/e) 0.87, 90% interval 0.82 to 0.93. Synonymous variants: 239 observed, 252.76 expected, observed/expected ratio (o/e) 0.95, 90% interval 0.85 to 1.05.
Homologues: Orthologues: chimpanzee WEE2 (99% identical), macaque WEE2 (95% identical), dog WEE2 (79% identical), pig WEE2 (74% identical), rabbit WEE2 (74% identical), mouse Wee2 (66% identical), rat Wee2 (65% identical), tropical clawed frog wee2 (51% identical), zebrafish wee2 (44% identical), Drosophila melanogaster Wee1 (35% identical). Paralogues in human: WEE1 (47% identical), PKMYT1 (23% identical), EIF2AK4 (21% identical), EIF2AK3 (19% identical), STK35 (17% identical), EIF2AK2 (16% identical), EIF2AK1 (16% identical), PDIK1L (11% identical).
Diseases named in the same sentence as WEE2 in open-access papers:
WEE2 is named in the same sentence as 6 diseases in open-access papers, as found by Europe PMC text mining. Sharing a sentence is not in itself a finding about the gene and the disease. The quoted sentences say what the papers report.
female infertility (4 papers, 2022 to 2023). Diminished or absent ability of a female to achieve conception. "Moreover, a study in mice indicated that Wee2-deficient caused fertilization failure and female infertility." (PMID 35154289, 2022). "In recent years, more and more evidence shows that WEE2 gene mutations may lead to fertilization failure and female infertility." (PMID 36589837, 2022). "Furthermore, Wee2-deficient mice exhibit fertilization failure and female infertility." (PMID 35154289, 2022). "In this study, we designed a target-sequencing panel with 22 female infertility-related genes, namely, TUBB8, PATL2, WEE2, and PANX1 and sequenced 68 primary infertility (PI) and recurrent pregnancy loss (RPL) patients." (PMID 35620457, 2022).
Infertility (2 papers, 2020 to 2024). "In addition to the studies from China that identified WEE2 mutations as a genetic basis for infertility, TFF has also been associated with mutations in PATL2." (PMID 32667031, 2020). "Alternatively, genes with no reported COI are enriched in gene sets associated with germ cell development and implicated in infertility mainly caused by spermatogenic failure (e.g., CATIP, CFAP65, CEP19) and oocyte/zygote/embryo maturation arrest (e.g., PADI6, REC114, WEE2)." (PMID 39202055, 2024).
tumor (1 paper, 2021). "We also compared expression levels of paired normal and tumor samples in the TCGA dataset, and found down-regulated levels of WEE1 and WEE2 and up-regulated levels of PKMYT1 in tumors." (PMID 34959223, 2021).
WEE2 also shares sentences with these, for which no sentence is quoted: aneuploidy (1 paper); breast carcinoma (1); colorectal cancer (1).